GLOD5 (glyoxalase domain containing 5)
Tractability: PROTAC: its protein half-life has been measured.
Gene: Protein-coding gene on chromosome X (48,761,747 to 48,773,648, forward strand). Ensembl gene ENSG00000171433.
Subcellular location (Human Protein Atlas): Mitochondria
Homologues: Orthologues: chimpanzee GLOD5 (99% identical), macaque GLOD5 (98% identical), dog GLOD5 (88% identical), rabbit GLOD5 (87% identical), pig GLOD5 (82% identical), guinea pig GLOD5 (81% identical), mouse Glod5 (75% identical), tropical clawed frog glod5 (57% identical), zebrafish glod5 (56% identical), rat Glod5 (55% identical), tropical clawed frog glod5 (53% identical), tropical clawed frog smyd5 (41% identical), and 1 more. Paralogues in human: MCEE (22% identical).
Diseases named in the same sentence as GLOD5 in open-access papers:
GLOD5 is named in the same sentence as 6 diseases in open-access papers, as found by Europe PMC text mining. Sharing a sentence is not in itself a finding about the gene and the disease. The quoted sentences say what the papers report.
breast carcinoma (1 paper, 2022). "According to such additional filter, six cancer-specific proteins in colon cancer (CEACAM8, CDH17, GLOD5, PPM1E, TRIM16, EPCAM) and one in breast cancer (CCR9) were identified." (PMID 36243758, 2022). "According to such parameters, six cancer-specific proteins in colon cancer (CEACAM8, CDH17, GLOD5, PPM1E, TRIM16, EPCAM), one in breast cancer (CCR9) and none in prostate cancer were identified." (PMID 36243758, 2022).
Microdontia (1 paper, 2019). Decreased size of the teeth, which can be defined as a mesiodistal tooth diameter (width) more than 2 SD below mean. "Since both pedigrees strongly imply that an X-linked basis for taurodontism, microdontia and dens invaginatus is a consistent triad phenotype, we further analyzed the segregation of the KIF4A and GLOD5 variants in other members of Family 1 from whom we had available DNA." (PMID 31616463, 2019).
cancer (1 paper, 2022). A tumor composed of atypical neoplastic, often pleomorphic cells that invade other tissues. "The results showed that the HIV peptides with the highest homology to TAAs identified in breast (CCR9), colon (EPCAM, GLOD5, CEACAM8) as well as prostate (NDUFS2) cancer and linked to most frequent HLA alleles (01:01; 02:01 and 24:02), are highly conserved across HIV isolates." (PMID 36243758, 2022).
GLOD5 also shares sentences with these, for which no sentence is quoted: colon cancer (1 paper); prostate carcinoma (1); taurodontism (1).